INS (insulin)
Diseases named in the same sentence as INS in open-access papers (continued):
Sharing a sentence is not in itself a finding about the gene and the disease.
Obesity (continued). "In summary, the findings of this study highlight the importance of microglial insulin signaling in the CNS control of energy metabolism and the sex-dependent differences observed during the progression of obesity." (PMID 35328354, 2022). "Though it has mostly been studied for its downstream effects on the translation of insulin, obesity has also been found to downregulate its mRNA levels in mouse adipose tissue, as CDKAL1 loss affects adipose mitochondrial function." (PMID 36128718, 2022). "Consistent with this, BDNF knockout mice develop mature-onset obesity with elevated levels of serum leptin, insulin, glucose, and cholesterol, and an increased body mass index." (PMID 35563026, 2022). "Comparison of indices of insulin-glucose homeostasis (mean ± SD) and sarcopenic obesity defined by D3Cr muscle mass and percent body fat." (PMID 36490255, 2022). "Adequate potassium intake has been shown to prevent obesity and MetS by regulating insulin secretion and carbohydrate metabolism." (PMID 36147306, 2022). "Under short-term (40 days) HFD feeding, a presymptomatic phase of obesity in WT mice, DGKε-KO mice show severe obesity and insulin resistant phenotype, whereas WT mice remain normal." (PMID 35153836, 2022). "To investigate the importance of hypothalamic microglial insulin signaling for immune function during obesity, we evaluated microglial cells in the arcuate nucleus (ARC), a key brain nucleus involved in systemic control of energy metabolism." (PMID 35328354, 2022). "Children with obesity also showed elevated plasma levels of fasting insulin, with increased HOMA-IR scores among IR subjects." (PMID 36552647, 2022). "Studies have shown that central inhibition of the cellular inflammatory pathway in the hypothalamus can promote leptin and insulin sensitivity, reduce high fat food intake, and consequently protect against high fat food induced obesity." (PMID 35911732, 2022). "In this study, we showed that microglial insulin signaling plays a sex-dependent role in the control of systemic energy homeostasis, with microglial InsR being involved in the progression of obesity most prominently in female mice." (PMID 35328354, 2022). "In another clinical trial, 6 months of dietary L-arginine supplementation improved whole body insulin-sensitivity in individuals with obesity." (PMID 35557517, 2022). "The anti-inflammatory adiponectin, downregulated in subjects with obesity and T2D, is also an insulin sensitizer." (PMID 35164764, 2022). "Together, these observations suggest that IL18-IL18r signaling in WAT adipocytes protects mice from obesity, insulin resistance and adipose inflammation by maintaining the homeostatic glucose metabolism and insulin signaling." (PMID 36482059, 2022). "We found that these Reg4 KO mice showed more sensitivity to HFD-induced obesity, including a higher body weight, higher fat pad tissue weight, decreased insulin sensitivity and reduced glucose tolerance." (PMID 35074011, 2022). "The relative abundance of A. muciniphila is inversely correlated with obesity in humans and it was shown to correct insulin resistance and obesity while increasing gut barrier function in a mouse model of diet-induced obesity." (PMID 35805168, 2022). "By decreasing calorie intake and resetting the metabolism, intermittent fasting can assist to reduce obesity and, as a result, insulin resistance." (PMID 36305681, 2022). "The consumption of animal foods, especially the calories and fat in red meat, leads to centripetal obesity that is an established factor for an increase in plasma insulin levels." (PMID 35079028, 2022). "The commonly observed high postprandial insulin clearance in people with obesity and T2D likely results from the relatively low insulin secretion rate, not an impaired adaptation of tissues that clear insulin." (PMID 35054781, 2022).
Obesity (continued). "In animal studies, male and female ESR1 gene knock-out mice have acquired metabolic syndrome characteristics including obesity due to decreased fatty acid oxidation, impaired glucose tolerance, and reduced insulin sensitivity." (PMID 35627115, 2022). "Human societies are facing an unprecedented epidemic of obesity, accompanied by liver steatosis, accumulated abdominal fat and reduced insulin sensitivity, altogether often leading to a clinical entity called metabolic syndrome." (PMID 36358339, 2022). "ABL1 is highly expressed in the subcutaneous fat of obese humans and high-fat diet-induced obese mice, and it is able to regulate diet-induced obesity by improving insulin sensitivity in subcutaneous fat." (PMID 35812879, 2022). "In obesity, the alterations related to energy generation, while in T2D the deep involvement of the NO synthesis and its relation to insulin signaling and inflammation were the most prominent functions." (PMID 35562924, 2022). "IL-1β is a strong proinflammatory cytokine, which is mainly produced by inflamed human adipose tissue and also immune cells in obesity but also impairs insulin signalling and increases lipolysis." (PMID 35883817, 2022). "Excess adiposity has thus almost become the norm, and trends in diagnosed diabetes trailed the obesity data with a 15–20 year delay owing to progressive damage from sustained hyperglycemia and impaired insulin action in the target tissues." (PMID 36615781, 2022). "Arterial plasma insulin concentration is as low as <60 pmol/L in lean people after an overnight fast and can reach values of up to ~1000 pmol/L in people with obesity postprandially." (PMID 35054781, 2022). "The usage of its inhibitor, sitagliptin, delayed the progression of obesity and insulin metabolism abnormalities in male offspring." (PMID 35454311, 2022). "It is predominantly produced in the liver but is also produced in increased amounts by adipocytes in obesity, which contributes to impaired insulin action." (PMID 36005598, 2022). "In this study, we found that the depletion of NF90–NF45 in murine islet β cells leads to hyperglycaemia owing to a decrement of plasma insulin and less expansion of islet mass under obesity-inducing metabolic stress like high-fat diet." (PMID 35614067, 2022). "As expected, individuals with obesity had higher fasting insulin levels and HOMA-IR than lean participants." (PMID 35334929, 2022). "Eating within two hours of bedtime is, however, regarded as a dietary habit that promotes obesity due to fat accumulation that results from insulin secretion and action of the appetite hormone leptin." (PMID 35329088, 2022). "Obesity affects numerous steps governing insulin action, including production in the pancreas, transport, and transmission of the insulin message by target cells." (PMID 36244663, 2022). "It has been widely acknowledged that reversing the obesity-related phosphorylation of PPARγ at Serine 273 (Ser273) improved insulin sensitivity." (PMID 36551260, 2022). "Accordingly, we aimed to evaluate the effects of matched 6% weight loss, induced by 6 weeks of a hypocaloric CRHP or CD diet, on β-cell function and insulin sensitivity, and pancreatic and gut hormone secretion in people with T2D and overweight or obesity." (PMID 36061897, 2022). "Further studies should focus on establishing what type of exercise provides greater improvements in insulin sensitivity in children and adolescents with obesity." (PMID 36364954, 2022). "Compared with the lean participants who received saline+vehicle (from protocol I), baseline (after vehicle) FPI and HOMA-IR were elevated, and peripheral insulin sensitivity (M) was reduced in individuals with obesity." (PMID 36066991, 2022). "Polyphenols targeting mTOR modulate inflammation, insulin resistance, and so on, which means that polyphenols affect obesity through the gut–liver–brain axis by targeting mTOR." (PMID 36501200, 2022).
Obesity (continued). "Our results indicated that despite varying levels of obesity, the lineages differ markedly in the transmission of regulatory factors of obesity, glucose homeostasis, and insulin sensitivity." (PMID 35419033, 2022). "Several maternal obesogenic factors contribute to obesity in offspring, including glucose, FFAs, insulin, leptin, IGF-1 and adiponectin." (PMID 36329895, 2022). "In this regard, early studies pertaining to the use of metformin to stimulate muscular glucose uptake showed metformin increased whole-body insulin-stimulated glucose uptake in patients diagnosed with T2D who presented with obesity." (PMID 35890085, 2022). "In obesity-induced IR, adipose tissue accumulation and its dysfunction result in the secretion of proinflammatory cytokines that impair insulin signaling." (PMID 36224569, 2022). "Obesity is an insulin‐resistant state (−29% insulin sensitivity); however, as long as beta‐cells produce a compensatory insulin secretion, glucose tolerance remains normal/near normal." (PMID 35913467, 2022). "In obesity, adipocytes secrete inflammatory adipokines which damage insulin signaling pathway, resulting in disorders of glucose and lipid metabolism." (PMID 35802723, 2022). "Increasing experimental studies have investigated the relationship between Pro12Ala polymorphism of PPARγ2 gene and various diseases such as T2DM, insulin sensitivity, obesity, cardiovascular diseases, Alzheimer's disease, and cancer." (PMID 35547362, 2022). "This index has been suggested to be more suitable in evaluating conditions related to insulin exposure, such as obesity." (PMID 36364954, 2022). "In a double-blind, placebo-controlled, crossover design, participants (35 lean women and 17 women with obesity) were randomized to receive 160 IU/1.6 mL of IN insulin or placebo in a counterbalanced order in the post prandial state." (PMID 35397638, 2022). "Serpin E1/PAI-1is a key regulator of fibrinolysis and has higher circulating levels in PCOS, which has also been positively related to circulating insulin levels, especially in the presence of obesity." (PMID 36714563, 2022). "Driven by this chronic impaired balance and excessive fat accumulation in the body, obesity has profound impact on tissue insulin sensitivity affecting systemic glucose homeostasis." (PMID 36419097, 2022). "It has been shown that obesity in sows leads to higher maternal plasma concentrations of INS and lower plasma levels of ADP in late pregnancy." (PMID 35737354, 2022). "In order to examine the function of mitochondrial, OXPHOS activities, relating to insulin sensitivity and resistance to diet-induced obesity, were measured." (PMID 36698477, 2022). "The implications of browning are generally considered protective in the setting of obesity, as brite adipocytes increase energy expenditure by increasing fatty acid oxidation and improve insulin sensitivity." (PMID 36388122, 2022). "In this study, we found that decanoate is clearly functionable to regulate glucose homeostasis by GLP-1 secretion via GPR84, improves insulin sensitivity, and prevents obesity." (PMID 35399667, 2022). "According to the literature, several factors influence changes in the body weight of D. melanogaster fed obesity diets, including age, mating, insulin/IGF signaling pathway modulation and leptin expression in the brain." (PMID 35204807, 2022). "Results from many studies that compared plasma insulin clearance in lean people and people with obesity and those with T2D are inconclusive." (PMID 35054781, 2022). "Deletion of GPR30 by reducing plasma insulin and leptin levels protects female mice from developing obesity, glucose intolerance and insulin resistance after nutritional challenge." (PMID 35273571, 2022). "Insulin and leptin resistance was consequently ameliorated, and obesity, T2DM, and NAFLD were repressed in mice." (PMID 36046814, 2022).
Obesity (continued). "Whilst not limited to individuals with obesity, liver steatosis is more prevalent in those with metabolic aberrations, such as excessive visceral (central) fat accumulation and insulin resistance." (PMID 35028685, 2022). "It is well established that impaired mitochondria structure and function occur in insulin-resistant skeletal muscle volunteers with T2D or obesity." (PMID 36093112, 2022). "Although some earlier studies have revealed the effect of inositol mediating glucose uptake by improving insulin sensitivity, the benefit of inositol supplementation in patients with overweight and obesity is not completely understood." (PMID 35664247, 2022). "Obesity and insulin dysregulation are closely related, so it was important to conduct the research on the obesity itself, as it can affect lamellar failure." (PMID 35883323, 2022). "Accordingly, inhibition of the inhibitor of nuclear factor kappa (IKK)/nuclear factor κB (NF-κB), Jun-N-terminal kinase (JNK) and inflammasome pathways can prevent weight gain, and restore insulin sensitivity in different obesity models." (PMID 35112705, 2022). "Several of the genes targeted by these miRNAs are also involved in pathways related to metabolism and obesity, including insulin resistance, lipolysis, adipocytokines, and thyroid hormone pathways." (PMID 35349487, 2022). "In our previous study, the Envigo fa/fa rats developed obesity accompanied by significantly increased plasma insulin, glucose intolerance, and IR at 33 weeks of age." (PMID 35589696, 2022). "Obesity is characterized by an accumulation of abdominal, particularly visceral fat, which is a determining factor in insulin resistance, especially in skeletal muscles." (PMID 36554057, 2022). "As expected, OGTT-related variables were different between the two obesity sub-samples, being the ObIR+ study group characterized by higher area under the curve for insulin and mean concentrations of glucose and insulin, as well as by decreased WBISI scores." (PMID 36552647, 2022). "Obesity has been shown to increase the secretion of androgens, insulin, insulin-like growth factor 1 (IGF-1), and growth hormones." (PMID 36694512, 2022). "Traditionally, obesity is considered one of the major factors of metabolic syndrome (MetS) including insulin sensitivity, hyperinsulinemia, hyperglycemia, and hypertension." (PMID 35873818, 2022). "In mice fed an HFD for 12 weeks to induce more profound obesity and metabolic dysregulation, Ad-Fis1 significantly increased both glucose and insulin tolerance compared with control mice." (PMID 35015731, 2022). "We demonstrate that, for the first time, MKP-2 expression was upregulated in liver tissue in humans with obesity and fatty liver disease and in insulin-responsive tissues in mice with obesity." (PMID 35745205, 2022). "The potent metabolic effects of metabolic surgery are not only shown by improved obesity, glucose tolerance, and insulin sensitivity." (PMID 36422274, 2022). "Animal models utilizing high-fat diets (plus glucose) to induce obesity, metabolic endotoxemia, and insulin resistances show alterations in the gut microbiota." (PMID 35629938, 2022). "Insulin sensitivity is a driver of adipose tissue partitioning, and abnormal fat deposition is a potent factor in the development and pathology of obesity." (PMID 35215546, 2022). "Ghrelin modulates the central appetite regulatory network, especially neuropeptide γ, and ghrelin interacts with a variety of adipocytokines, such as leptin and insulin, and plays an important role in the pathological process of obesity." (PMID 35069014, 2022). "In conclusion, the effects of TRF on glucose metabolism and insulin sensitivity in individuals with overweight or obesity are mixed." (PMID 36432465, 2022). "In this light, the body composition and insulin improvements predicted with increased PA present significant potential to enhance the long-term health of Māori women with overweight and obesity." (PMID 35886612, 2022).
Obesity (continued). "They show higher insulin sensitivity than their controls, protecting them against obesity-induced IR." (PMID 36224569, 2022). "Resistin is a kind of adipokine that can resist insulin, increase blood sugar levels, and promote fat cell proliferation which facilitates obesity." (PMID 35418966, 2022). "Here, we further confirmed that the HF before and during pregnancy significantly induced obesity and dramatically worsen glucose tolerance, insulin sensitivity, and lipid metabolism in the gestational mice." (PMID 36245521, 2022). "As a common intensive nutrition and lifestyle intervention strategy for obesity, IF has been shown to achieve weight reduction and improve insulin resistance and metabolic health." (PMID 36432420, 2022). "Literature on the regulation of TSH in euthyroid individuals with obesity, is contradictory and there is a paucity of studies investigating the combined effects of both lipid and insulin in patients with normal TSH and thyroid hormone levels." (PMID 35544473, 2022). "Although, obesity is frequently present, several studies have reported normal insulin levels and higher insulin sensitivity in PWS than in BMI-matched children and adults." (PMID 35150573, 2022). "This molecule is a multifunctional glycoprotein that imposes metabolic effects such as obesity, peripheral insulin sensitivity decrease, diabetes, and non-alcoholic fatty liver diseases, mainly at higher levels." (PMID 35682868, 2022). "Adiponectin and leptin are adipokines that considerably influence obesity-related metabolic diseases by modulating fat metabolism, energy homeostasis, and insulin sensitivity." (PMID 35889740, 2022). "In a recent study, it has been showed that ablation of IL‐10 improved insulin sensitivity and inhibited diet‐induced obesity, also in another study, IL‐10 was indicated to be decreased in childhood obesity." (PMID 35266264, 2022). "During obesity, the accumulation of elevated fat stores triggers a global, and permanent, inflammatory status that eventually leads to insulin and leptin resistance, paving the way to obesity-related co-morbidities." (PMID 36507349, 2022). "A. muciniphila modulates obesity by regulating metabolism and energy hemostasis and improving insulin sensitivity and glucose hemostasis." (PMID 35455732, 2022). "By this concept, in response to any physiological change in insulin sensitivity (e.g., due to obesity, pregnancy, or puberty), an individual would mount an appropriate insulin secretion response, according to the disposition index equation." (PMID 35163746, 2022). "T2DM is a lipotoxicity-related disease in which obesity-induced miR-802 impairs insulin transcription by inhibiting NeuroD1 and reduces insulin secretion by inhibiting calcium influx field." (PMID 36147580, 2022). "The expected compensatory increase in glucose-stimulated insulin secretion in obesity was observed in islets isolated from β-Xbp1+/+Ob mice." (PMID 35316840, 2022). "Here the authors report that global or adipocyte-specific deletion of REDD1 inhibits diet induced obesity, insulin resistance, liver steatosis and inflammation in mice, at least in part via reduced atypical NF-κB activation." (PMID 36272977, 2022). "Increased local concentration of glucocorticoids rather than systematically elevated glucocorticoid levels impairs insulin and leptin sensitivity, which ultimately results in metabolic disease, including Cushing’s syndrome, obesity and type 2 diabetes." (PMID 36131216, 2022). "Genetic manipulations leading to depletion of JNK prevent obesity by decreasing adiposity and ameliorating insulin sensitivity and IR signalling." (PMID 35128745, 2022). "PCOS is a complex disease with genetic and environmental components, and genes related to obesity and insulin metabolism appear to be involved in the etiology of this syndrome." (PMID 36522620, 2022).